YTHDF1 (YTH N6-methyladenosine RNA binding protein F1)
Diseases named in the same sentence as YTHDF1 in open-access papers (continued):
Sharing a sentence is not in itself a finding about the gene and the disease.
cancer (continued). "YTHDF1 then binds to PKM2 mRNA to increase PKM2 expression and glycolysis in cancer cells, accelerating the genesis and metastasis of breast cancer." (PMID 37582735, 2023). "Next, DLGAP1-AS2 and YTHDF1 work together to promote the expression of c-MYC mRNA, accelerate the growth of cancer cells and enhance glycolysis." (PMID 37582735, 2023). "Bioinformatic analysis of N1-methyladenosine (m1A) regulators (TRMT6/61A, RRP8, ALKBH1/3, YTHDF1-3, YTHDC1) in LUSC revealed that most of the m1A regulators were significantly upregulated in cancer tissues compared to normal samples." (PMID 37612540, 2023). "Thus, YTHDF1 might be a new therapeutic and prognostic target for cancers." (PMID 36707507, 2023). "To further understand the roles of YTHDF1, IGF2BP3 and NKAP in other cancers, we collected their expression levels from pan-cancer analysis." (PMID 35963644, 2022). "METTL3, methyltransferase 14, N6-adenosine-methyltransferase complex catalytic subunit (METTL14) and YTH N6-methyladenosine RNA binding protein 1/2 (YTHDF1/2) are m6A modifiers in human NSCLC and play oncogenic roles in this cancer." (PMID 35441574, 2022). "PCR results of cancer and adjacent paracancerous tissues showed that KIAA1429 and YTHDF1 were highly expressed in cancer tissues, which was consistent with our bioinformatics results." (PMID 35075167, 2022). "It was observed that CDON, YTHDF1 and METTL3 were highly expressed in cancer tissues compared to that of in corresponding normal tissues, suggesting that there was a positive relationship between FRAS1, CDON, and METTL3/YTHDF1." (PMID 36008805, 2022). "YTHDF1/eEF-2 complex binding with IGF2BP3, can stabilize PDK4 through m6A manner, further promote glycolysis, and promote cancer progression." (PMID 35022030, 2022). "The data was obviously showed that YTHDF1, IGF2BP3 and NKAP were highly expressed in most cancer types." (PMID 35963644, 2022). "An increasing number of studies have confirmed that m6A writers (METTL3, METTL14, KIAA1429, WTAP), erasers (FTO and ALKBH5) and readers (YTHDC1, YTHDC2, YTHDF1, YTHDF2 and HNRNPC) have distinct functions within different types of cancer cells." (PMID 35042525, 2022). "More importantly, YTHDF1, IGF2BP3 and NKAP were also highly expressed in pan-cancer, which provided the promise of YTHDF1, IGF2BP3 and NKAP as potential therapeutic targets." (PMID 35963644, 2022). "They further demonstrated that HPSCC tumorigenesis induced by YTHDF1 is dependent on iron metabolism and regulates transferrin receptor protein (TFRC) expression in this cancer." (PMID 35186927, 2022). "The regulatory network of “writer” METTL3, “reader” YTHDF1, and “target” FRAS1 inspires the understanding of m6A-dependent gene regulatory mechanism in cancer biology, which offers a possibility of m6A regulators as promising biomarkers in NSCLC." (PMID 36008805, 2022). "We can seen that YTHDF1 was related to the TME of 21 cancers, the immune score of 19 cancers, and the stromal score of 15 cancers." (PMID 35075167, 2022). "YTHDF1 was reported to mediate the m6A-increased translation of Snail mRNA and thus regulate EMT in cancer cells." (PMID 33795663, 2021). "We found that cell cycle, ERBB signaling pathway, oocyte meiosis, pathways in cancer, spliceosome, ubiquitin mediated proteolysis, and WNT signaling pathway were distinctly enriched in high YTHDF1 expression group." (PMID 34434939, 2021). "The GSEA results demonstrated that high YTHDF1 expression was distinctly correlated to cell cycle, ERBB signaling pathway, oocyte meiosis, pathways in cancer, spliceosome, ubiquitin mediated proteolysis, and WNT signaling pathway." (PMID 34434939, 2021).
cancer (continued). "However, the role of YTHDF1 in prognosis and immunology in human cancers remains largely unknown." (PMID 34026603, 2021). "ALKBH3 (p < 0.001), TRMT61A (p < 0.001), YTHDF1 (p < 0.001), ALKBH1 (p < 0.001), and TRMT6 (p < 0.001) in cancer tissues were significantly up-regulated compared to those in normal tissues (p < 0.001)." (PMID 34195072, 2021). "YTHDF1 promotes the translation of EIF3C and therefore enhances the total translational output, inducing cancer progression and metastasis." (PMID 33795663, 2021). "YTHDF1 promotes ovarian cancer progression by regulating EIF3C translation and plays an important role in other cancers including lung, gastrointestinal, liver, and oral cancers." (PMID 34677810, 2021). "m6A was reported to be involved in the EMT of cancer cells and modulated via the methyltransferase METTL3, demethylase ALKBH5, and its reader YTHDF1." (PMID 33364952, 2020). "However, the significance of YTHDF1 in cancer is largely unknown." (PMID 32742460, 2020). "However, the link between YTHDF1 and cancer is largely unknown." (PMID 32111180, 2020). "However, the relationship between YTHDF1 and cancer is largely unknown." (PMID 31131257, 2019). "To study the role of Ythdf1 in the malignant behavior of cancer in patients, we classified patients with CRC into four groups by Ythdf1 staining intensity." (PMID 29484125, 2018). "Furthermore, some genes (e.g., FXR2, METTL16) generally show copy number losses in pan-cancer, while some (e.g., IGF2BP3, YTHDF1) primarily exhibit copy number amplifications." (PMID 40867324, 2025). "In addition, the IGF2BP3 and YTHDF1/eEF-2 complexes increase PDK4 mRNA stability through the m6A modification system, a process that promotes the glycolytic process of cancer cells and accelerates CC development." (PMID 40356909, 2025). "YTHDF1, along with YTHDF2 and YTHDF3, redundantly suppresses the IFN‐γ response by destabilizing IRF1 mRNA, suggesting that these proteins can serve as viable therapeutic targets in cancer immunotherapy." (PMID 39587835, 2025). "Remarkably, the concurrent inhibition of m6A readers YTHDF1 and YTHDF2 in combination with ICIs may mitigate resistance to immunotherapy in cancer." (PMID 39987091, 2025). "The binding of the YTHDF1 protein to m6A-modified TRIM29 promotes the translation of TRIM29 in cisplatin-resistant OC cells, enhances the cancer stem cell characteristics in cisplatin-resistant OC cells, and then promotes the development of malignant tumours." (PMID 40356909, 2025). "YTHDF1 was highly expressed in cancer cells, while IGF2BP1 did not exhibit statistically significant differences." (PMID 39185313, 2024). "In addition, there is a higher binding affinity between YTHDF1 and CDS of Snail mRNA in cancer cells undergoing EMT." (PMID 39136000, 2024). "In numerous cancers, there is a consistent observation of dysregulated expression of key enzymes involved in m6A modification, including "writers" (such as METTL3, METTL14, WTAP), "erasers" (like FTO, ALKBH5), and "readers" (including YTHDF1, YTHDF2, YTHDF3)." (PMID 38270643, 2024). "We discovered that radiotherapy (RT) increased YTHDF1 expression in dendritic cells (DCs) of PBMCs from patients with cancer, but not in other immune cells tested." (PMID 39325547, 2024). "This review focuses on RBPs, particularly HuR, NONO, IGF2BP2 and 3, Musashi1 and 2, Lin28, RBM, Pumilio, YTHDF1, and AUF1, which are most extensively studied in association with cancer drug resistance." (PMID 38328550, 2024). "In murine cancer models, IR activation of STING/IFN-I signaling induced YTHDF1 expression." (PMID 39325547, 2024). "In addition, m6A‐recruited the binding proteins, YTHDC1, YTHDC2, YTHDF3, and FMR1 were inversely correlated, while HNRNPC, HNRNPA2B1, YTHDF1, and RBMX positively correlated TSs in most cancer types." (PMID 36239411, 2023).
cancer (continued). "Currently, m6A protein machineries found in cervical cancer including METTL3, YTHDF1 and FTO all play a role in promoting the occurrence of cancer, and whether other machineries are involved in CC can be explored in the future." (PMID 35813486, 2022). "Intriguingly, Wnt-signaling in intestinal stem cells (ISCs) could induce YTHDF1 expression to promote the translation of TCF7L2/TCF4, inferring a positive feedback loop between YTHDF1-mediated m6A and Wnt signaling that promoted cancer stemness." (PMID 36009465, 2022). "Interestingly, the enhanced levels recruited the binding of YTHDF1, which promoted the translation of MYC mRNA and increased glycolysis and cancer progression." (PMID 35186927, 2022). "Furthermore, YTHDF1 and YTHDF2 impacted cancer via binding m6A sites in the 3′-UTR of EGFR transcription and contributed to aberrant activities of downstream signal pathways." (PMID 36517820, 2022). "In another interesting experiment, targeting YTHDF1 effectively re-sensitizes cisplatin-resistant colon cancer by modulating GLS-mediated glutamine metabolism, providing a novel strategy for targeted glutamine therapy for cancer." (PMID 35794625, 2022). "Different relationships between YTHDF1 expression and gene markers of immune cell infiltration in PRAD and BLCA may explain why there are different survival outcomes in various cancer types." (PMID 34026603, 2021). "YTHDF1 expression had a strong relationship with dendritic cell in 12 cancer types, macrophage in 9 cancer types, neutrophil in 8 cancer types, CD8+ T cells in 13 cancer types, B cells in 10 cancer types and CD4+ T cells in 6 cancer types." (PMID 34026603, 2021). "In addition, m6A “readers” such as YTHDF1 and HNRNPC also served as promising biomarkers in cancer stemness aspects." (PMID 34345203, 2021). "For example, YTHDF1 and IGF2BP3 were up-regulated in 11 cancer types except for THCA." (PMID 33718187, 2021). "Our results indicate that the YT521-B homology (YTH) domain family (“readers”), especially YTHDF1, YTHDF3, and YTHDC2, might play a significant role in the detection, progression, and prognosis of COAD, indicating that they are promising cancer biomarkers." (PMID 32596399, 2020). "In addition to the writers and erasers of m6A modification, the readers, including YTHDF1, YTHDF2, and IGF2BP1, may represent potential biomarkers for responses to cancer immunotherapies." (PMID 39987091, 2025). "Tissue factor pathway inhibitor 2 (TFPI‐2) mRNA is m6A‐modified and stabilized by binding to YTHDF1, which upregulates TFPI‐2 expression and suppresses tumor growth, migration, and invasion, but removal of m6A‐modification by FTO reduces TFPI‐2 expression and promotes cancer progression." (PMID 40448344, 2025). "Mechanistically, circRHBDD1 interacts with the m6A-binding protein YTHDF1 (YTH N6-methyladenosine RNA-binding protein F1), favoring PIK3R1 (phosphoinositide-3-kinase regulatory subunit 1) translation and activating the PI3K/AKT pathway that contributes to the metabolic shift in cancer cells." (PMID 38398157, 2024). "Therefore, we believe that high expression of YTHDF1 may promote the expression of SLC2A3, promote the glycolysis of ESCA, and finally promote the progress of cancer." (PMID 35401696, 2022). "In addition, PD1/PD-L1 checkpoint blockade is regulated by YTHDF1 (m6A reader) and FTO (eraser), and m6A modulators may be potential anti-cancer immunotherapy targets." (PMID 35281840, 2022). "Compared with the control group, expression levels of HNRNPC, YTHDF1, KIAA1429, RBM15, YTHDF2, and METTL3 in cancer group were significantly up-regulated (P < 0.05), while expression levels of FTO, ZC3H13, METTL14, YTHDC1, and WTAP in cancer group were significantly down-regulated (P < 0.05)." (PMID 33193582, 2020).
cancer (continued). "The results showed that YTHDF1 silencing formed smaller tumors.Then we validated the expression of CD133, CD44, ALDH1, OCT4, and Lgr5 in xenograft tumors by RT-qPCR, the results showed that YTHDF1 silencing downregulated the expression of CRC cancer stem cell markers in xenograft tumors." (PMID 31131257, 2019). "Thus, the balance of YTHDF1 expression and its targeted m6A-modified mRNAs or interacting proteins between normoxia and hypoxia conditions is important both for non-pathological homeostasis and various human cancers." (PMID 31653849, 2019). "The expression study indicated that c-Myc has a correlation with YTHDF1, but not with other family, though we found the c-Myc binding site(s) around the transcription initiation regions of those family genes through the study of chromatin immunoprecipitation database (ChIP-atlas) in cancer cells." (PMID 29484125, 2018). "Mechanistic studies dissecting the low-complexity domains and condensate behavior argue for nonidentical roles of YTHDF1 and YTHDF2, while cancer models continue to implicate IGF2BPs in stabilizing drug-resistance transcripts (e.g., ABCB1)." (PMID 41280938, 2025).
infection (14 papers, 2016 to 2024). The state of being infected such as from the introduction of a foreign agent such as serum, vaccine, antigenic substance or organism. "This revealed that YTHDF1, 2, and 3 are cleaved over the course of infection, with rapid loss of full-length protein and the appearance of an ∼50- to 55-kD fragment corresponding to the predicted size of the C-terminal fragment produced by cleavage at LTT/SY′G." (PMID 33849973, 2021). "We first found that YTHDF1-3 colocalize and interact with HuR, a known SG marker, at early phases of infection in SGs, but these reader proteins were cleaved at a later phase, resulting in enhanced CVB3 replication (VP1 synthesis and 2A transcription)." (PMID 39597541, 2024). "In the current study, we identified a novel lysine modification, Klac of YTHDF1 and showed that the lactylation of YTHDF1 was enhanced by SFTSV infection." (PMID 39496835, 2024). "The downregulation of YTHDF1 responding to time of infection and viral inoculum indicated a virus-driven process." (PMID 39496835, 2024). "To eliminate a potential role of organized cell death programs in the cleavage of YTHDF1 to 3 in EV-infected cells, we carried out infections in cells cotreated with escalating concentrations of Z-VAD-fmk, a pan-caspase inhibitor." (PMID 33849973, 2021). "In aggregate, our findings indicate that YTHDF1 to 3 are cleaved by EV 2Apro at predicted consensus 2Apro cleavage sites early during infection, prior to the onset of bulk viral translation and host CPE." (PMID 33849973, 2021). "Recently, it has also been reported that reader proteins YTHDF1-3 can promote the formation of cytosol stress granules (SG), a cellular response to stress conditions such as heat shock, hypoxia, irradiation, toxin, infection, etc.." (PMID 39597541, 2024). "Additionally, Due to SFTSV infection-induced downregulation of YTHDF1, siYTHDF1 may have an insignificant effect on SFTSV RNA." (PMID 39496835, 2024). "In this study, we provide the first evidence that the m6A modification level was enhanced in macrophages in vitro after TP infection and that the writer, METTL3, and the reader, YTHDF1, were upregulated both in vitro and in secondary syphilitic lesions." (PMID 35444649, 2022). "Immunofluorescence (IF) signals of both YTHDF1 and YTHDF2 in GC axons were also significantly reduced after infection of shYthdf1 or shYthdf2, suggesting that axonal YTHDF1 and YTHDF2 signals are specific." (PMID 34643063, 2021). "Over the course of infection, levels of the assayed writers (METTL3, METTL14, and WTAP) and readers (YTHDC1, YTHDF1, and YTHDF2) remain unchanged." (PMID 33243990, 2020). "The role of YTHDF1, 2, and 3 on HIV-1 genome degradation early during infection is a bit more difficult to explain." (PMID 29643844, 2018). "Upon infection with CVB3, the results revealed that the knockdown of YTHDF1 and YTHDF2 resulted in significant reductions in CVB3 RNA copies, VP1 proteins, viral titres and GFP expression, whereas the knockdown of YTHDF3 led to a decrease in only CVB3 RNA copies and GFP expression." (PMID 39339923, 2024). "They showed that overexpression of YTHDF1–3 proteins in HEK293T cells enhanced HIV-1 mRNA and protein expression in a single-cycle infection, and that overexpression or knockout of YTHDF2 in CEM-SS T-cells increased or decreased HIV-1 replication and protein expression, respectively." (PMID 27371828, 2016). "Additionally, they demonstrated that the YTHDF1-3 proteins, especially YTHDF2, can bind to these m6A decoration and consequently increase the expression of HIV-1 genomic RNA (gRNA) and p24 capsid protein, ultimately enhancing virus proteins translation at 48 h post-infection (hpi)." (PMID 33746967, 2021). "Thus, our results indicate that YTHDF2, but not YTHDF1 and YTHDF3, decreases HIV-1 RNA abundance in a single round infection assay." (PMID 35101069, 2022).
infection (continued). "Similarly, depletion of the YTHDF2, but not YTHDF1 or YTHDF3, increased the levels of HIV-1 transcripts in a single round infection assay." (PMID 35101069, 2022).
bacterial infection (9 papers, 2013 to 2024). "YTHDF1 is essential for IECs’ defense against bacterial infection by regulating Traf6 expression, a pivotal regulator of TLRs and NF-κB signaling." (PMID 38830900, 2024). "In the intestinal immune response to bacterial infection, YTHDF1 can facilitate the immune inflammatory response by regulating the transcription of TRAF6." (PMID 36550542, 2022). "Similar study supported a model in which m6A modifications in the Traf6 transcript regulated the intestinal immune response to bacterial infection via a complex consisting of YTHDF1, DDX60, and the Traf6 transcript." (PMID 36578521, 2022). "In addition, macrophages deficient in METTL14 or YTHDF1 exhibit impaired SOCS1 induction, leading to increased pro-inflammatory cytokine and chemokine production, which exacerbates responses to bacterial infections." (PMID 39686999, 2024). "However, another study shows the opposite result that YTHDF1 induces proinflammatory IL-1β production in macrophages following bacterial infection." (PMID 38874470, 2024). "Specifically, YTHDF1 facilitates the transcription and expression of m6A-modified Traf6 mRNA in a DDX60-dependent manner, ultimately impairing IECs’ defense against bacterial infection." (PMID 38830900, 2024). "It is believed that YTHDF1 and YTHDF3 are able to enhance the translation of target genes and facilitate inflammation by recognizing the m6A modification against bacterial infection in humans and mouse." (PMID 37298300, 2023). "The increase in METTL14 and the increase in METTL14 mediate the increase in the m6A modification of SOCS1, and the increase in SOCS1 mRNA stability through YTHDF1 is necessary to maintain the negative feedback control of macrophage activation in response to bacterial infection." (PMID 39337381, 2024).
metabolic disease (5 papers, 2022 to 2025). A congenital disorder (due to inherited enzyme abnormality) or acquired (due to failure of a metabolically important organ) disorder resulting from an abnormal metabolic process. "Here, we unveil a previously unrecognized METTL14/METTL3/G6pc mRNA m6A/YTHDF1 and YTHDF3/G6pc biosynthesis/HGP pathway governing HGP in health and metabolic disease." (PMID 40278833, 2025).
cardiovascular disease (3 papers, 2023 to 2025). "For cardiovascular diseases, YTHDF1 has been reported to associate with the proliferation and differentiation of cardiomyocytes." (PMID 39936952, 2025).
digestive system neoplasm (3 papers, 2021 to 2023). A neoplasm (disease) that involves the digestive system. "Current research overwhelmingly suggests that YTHDF1 is highly expressed in gastrointestinal tumors and is associated with poor prognosis, indicating its carcinogenic role." (PMID 38202722, 2023).